FAM90A12 (family with sequence similarity 90 member A12)
Synonyms: FAM90A12P
Tractability: No criterion of Open Targets' tractability assessment is met for any kind of drug.
Gene: Protein-coding gene on chromosome 8 (8,027,636 to 8,030,646, reverse strand). Ensembl gene ENSG00000254229.
Subcellular location (Human Protein Atlas): Nucleoplasm; Nucleoli
Homologues: Orthologues: mouse Fam90a1b (28% identical), mouse Fam90a1a (27% identical), rat Fam90a1l1 (26% identical). Paralogues in human: FAM90A23 (98% identical), FAM90A13 (98% identical), FAM90A15 (98% identical), FAM90A14 (98% identical), FAM90A24 (98% identical), FAM90A16 (97% identical), FAM90A17 (97% identical), FAM90A5 (97% identical), FAM90A9 (97% identical), FAM90A8 (97% identical), FAM90A18 (97% identical), FAM90A19 (97% identical), and 9 more.